GPNMB (glycoprotein nmb)
Diseases named in the same sentence as GPNMB in open-access papers (continued):
Sharing a sentence is not in itself a finding about the gene and the disease.
Parkinson disease (continued). "When two genes linked to increased Parkinson’s risk converge on a lysosome, LRRK2 mutation enhances lysosomal release of soluble GPNMB potentially contributing to synuclein pathology." (PMID 41406219, 2025). "Several patients with Parkinson’s and Gaucher diseases also had liver and pulmonary disease, which are likely to be an additional source of the circulating plasma gpNMB protein." (PMID 41152894, 2025). "In brain regions that are important in Parkinson’s disease (PD) (the substantia nigra and striatum), GPNMB is almost exclusively expressed in macrophage-like microglia and, to a lesser extent, in lysosome-rich astrocytes." (PMID 41406219, 2025). "The risk allele increases GPNMB transcription and GPNMB protein levels in the CSF highlighting GPMNB as a potential biomarker for Parkinson's disease." (PMID 41406229, 2025). "The expression levels of GPNMB are elevated in the substantia nigra of patients with Parkinson's disease (PD) and the GFAP-positive astrocytes." (PMID 39263169, 2024). "CSF levels of GRN, MMP‐10, and GPNMB were altered in Alzheimer's disease, preclinical Alzheimer's disease, and Parkinson's disease, respectively." (PMID 36504281, 2023). "GPNMB is a transmembrane protein, which traffics to the plasma membrane and has been shown to interact with α-synuclein, increasing the progression of Parkinson’s disease." (PMID 37949225, 2023). "Compared with these studies, we used a stricter P value cutoff with multiple testing correction and were able to replicate associations between BIN1, CD33 and Alzheimer’s disease and those between GPNMB and Parkinson’s disease." (PMID 37118290, 2022). "Most strikingly, the heightened expression of GPNMB has been associated with amyotrophic lateral sclerosis (ALS), Parkinson’s disease and Alzheimer’s Disease, all of which have pathogenic amyloids as major components of the disease progression." (PMID 34207849, 2021). "For example, the non-coding variant rs199347, associated with Parkinson’s disease exclusively, affects the expression of protein-coding gene GPNMB (Glycoprotein Nmb) in the human brain while sparing other tissues." (PMID 31811942, 2019). "Moreover, GPNMB ameliorates astrocyte-mediated inflammation through CD44 receptor in Parkinson’s disease (PD)." (PMID 40653468, 2025). "The first limitations of our research include the focus on carriers of the GPNMB variant, rather than individuals with a clinically confirmed diagnosis of Parkinson’s disease." (PMID 37744396, 2023). "In addition, compared to 59 healthy individuals, GPNMB was elevated in the plasma of 731 Parkinson’s patients." (PMID 37483347, 2023). "In addition, an analysis of human brain samples showed higher expression of GPNMB in the substantia nigra in patients with sporadic Parkinson's disease than in healthy controls." (PMID 37786733, 2022). "Both GPNMB gene expression and protein levels have been shown to be elevated within brain regions of Parkinson’s disease patients, and functional follow-up in these same studies indicated that GPNMB may act through suppression of the inflammatory response." (PMID 33417599, 2021). "GPNMB has also been identified as a biomarker in CSF for neuropathic forms of Gaucher’s disease (types 2 and 3) that are caused by mutations in GBA, a Parkinson’s disease-associated gene." (PMID 31721001, 2019). "Interestingly, increased levels of GPNMB have been observed in brain samples and/or the cerebrospinal fluid of patients with neurodegenerative diseases such as amyotrophic lateral sclerosis, Parkinson’s disease, Alzheimer’s disease, and multiple sclerosis." (PMID 37047799, 2023). "Our MR suggested that GPNMB inhibitors could be re-purposed to treat Parkinson’s disease." (PMID 33417599, 2021).
Parkinson disease (continued). "Glycoprotein nonmetastatic melanoma protein B (GPNMB) is a transmembrane glycoprotein that has recently been associated with an emerging role in neuroinflammation, which has been reported to be increased in post-mortem brain samples from AD and Parkinson’s disease patients." (PMID 33947460, 2021). "Here, we highlighted the role of 3 genes (GPR88, GPNMB, and GMPR) showing higher expression in CM (FC > 4) and that could be interesting key players of CM since higher expression of them are also associated to Parkinson's and Alzheimer's diseases." (PMID 32801995, 2020). "Genome wide association studies (GWAS) for Parkinson’s disease (PD) have previously revealed a significant association with a locus on chromosome 7p15.3, initially designated as the glycoprotein non-metastatic melanoma protein B (GPNMB) locus." (PMID 28391543, 2017). "The overexpression of GPNMB protected against dopaminergic neurodegeneration in a 1-methyl-4-phenyl-1,2,3,6-tetrahydropyridine (MPTP) mouse model of Parkinson’s disease." (PMID 37047799, 2023). "Data also link GPNMB to neurodegeneration, including cerebral ischemia, amyotrophic lateral sclerosis (ALS), Alzheimers Disease (AD), Multiple Sclerosis (MS), and Parkinson Disease (PD)." (PMID 30586924, 2018). "Mendelian randomization analyses suggested causal roles for several proteins, for example, ApoE, CD33, and GRN in Alzheimer's disease, MMP‐10 in preclinical Alzheimer's disease, SIGLEC9 in amyotrophic lateral sclerosis, and CD38, GPNMB, and ADAM15 in Parkinson's disease." (PMID 36504281, 2023). "Perhaps counterintuitively, elevated levels of GPNMB are neuroprotective in Parkinson’s and ALS models, and the protein has not been described as a component of amyloid plaques." (PMID 34207849, 2021). "Mean plasma concentrations of gpNMB in Gaucher patients with PD were slightly but not significantly greater than in GD3 and GD1 patients without identified Parkinson’s disease." (PMID 41152894, 2025).
Alzheimer disease (29 papers, 2018 to 2026). A progressive, neurodegenerative disease characterized by loss of function and death of nerve cells in several areas of the brain leading to loss of cognitive function such as memory and language. "Microglia express GPNMB in the brains of Alzheimer's disease and Nasu-Hakola disease, PRKCA is associated with neural basis of episodic remembering in healthy individuals and KCNMB4 is downregulated in hippocampal granule neurons following seizure activity." (PMID 38632500, 2024). "GPNMB has also been described in amyloid plaque-associated microglia in Alzheimer’s disease and recently identified as one the top up-regulated proteins in response to progranulin deficiency." (PMID 39217398, 2024). "Microglia_2 expresses GPNMB which labels lipid-associated microglia in mice, is expressed in microglia in Alzheimer’s disease and which we detected in a subset of microglia using immuno-fluorescence." (PMID 37217978, 2023). "GPNMB has been reported to have anti-inflammatory and neuroprotective functions in the brain and to be associated with several neurodegenerative diseases (asemyotrophic lateral sclerosis and Alzheimer’s disease)." (PMID 34639184, 2021). "The strongest consistent signal across population groups was the higher proportion of GPNMB+ microglia in individuals with a clinical diagnosis of Alzheimer’s dementia and/or steeper slope of cognitive decline; this signal was found in all three brain regions." (PMID 40584839, 2025). "The results from our study suggest a potential clinical application for the GPNMB protective factor as a biomarker of the Alzheimer’s disease continuum." (PMID 37510803, 2023). "High levels of GPNMB expression in Alzheimer’s disease brains have been proposed as a potential biomarker of Alzheimer’s disease." (PMID 34827437, 2021). "On the other hand, increasing GPNMB levels were reported in patients with Alzheimer’s disease, suggesting anti-inflammatory, regenerative, and neuroprotective roles." (PMID 32585848, 2020). "Subcluster 2 expressed high levels of white matter associated genes (NRP1, MERTK, and NCKAP5) while subcluster 3 displayed a disease‐associated signature (STARD13, MITF, GPNMB, and DPYD) previously observed in Alzheimer's disease (AD) and Multiple Sclerosis (MS)." (PMID 41283828, 2026). "In an Alzheimer's disease mouse model, GPNMB was strongly upregulated in microglia subsets, suggesting that GPNMB may be part of the unique microglial activation state in neurodegenerative diseases." (PMID 37786733, 2022). "Interestingly, our finding of GPNMB upregulation in activated microglia is supported by recent results in Alzheimer’s disease brains." (PMID 34919646, 2022). "The association between GPNMB and PD cognitive function has not been reported, but its function in Alzheimer's disease (AD), has been profoundly studied." (PMID 32983228, 2020). "We found that GPNMB+ microglia showed the same robust and statistically significant association (higher abundance) in the DLPFC in these two published studies, in individuals with a clinical diagnosis of MCI or Alzheimer’s dementia, and with steeper slope of cognitive decline." (PMID 40584839, 2025). "In recent years, some scholars have found that GPNMB-expressing microglia were significantly increased and activated in the brain tissue of patients with Alzheimer's disease (AD), suggesting that GPNMB may have a connection with neuroinflammatory response in AD." (PMID 37919457, 2023).
glioma (29 papers, 2010 to 2025). A benign or malignant brain and spinal cord tumor that arises from glial cells (astrocytes, oligodendrocytes, ependymal cells). "Several studies have previously linked GPNMB to the promotion of glioma cell motility, cell growth and angiogenesis." (PMID 38566120, 2024). "For example, GPNMB has been found to be highly upregulated in human glioma-associated microglia/macrophages, which are the predominant source of GPNMB transcripts." (PMID 31097021, 2019). "For example, elevated GPNMB in glioma tissue stems largely from reactive glioma-associated phagocytosing microglia and macrophages (GAMs)." (PMID 30586924, 2018). "GPNMB has been identified in disease-associated microglia in multiple disorders, including AD and gliomas, which has led to speculation on the role of GPNMB in disease susceptibility for PD." (PMID 37359515, 2023). "Moreover, GPNMB is overexpressed in various cancer types (i.e., its overexpression is associated with glioma)." (PMID 28347118, 2015). "The impact of host-derived GPNMB on tumor growth was confirmed in two distinct murine glioma cell lines in organotypic brain slices from GPNMB-KO and control mice." (PMID 38566120, 2024). "In contrast, cultured PDGFb-driven RCAS glioma cells (≤ 7 passages) showed lower levels of GPNMB expression (n = 3, p = 0.3555) similar to astrocytes." (PMID 38566120, 2024). "Innate immune cell infiltration, such as TAMs and neutrophils, contribute in TME of gliomas to higher level of GPNMB." (PMID 38566120, 2024). "Taken together, these results imply a detrimental role of host-derived GPNMB in modelling the immune cell composition through TAMs in the TME of high-grade glioma." (PMID 38566120, 2024). "GPNMB is a type I transmembrane glycoprotein that is overexpressed in several cancers, including glioma and melanoma." (PMID 38566120, 2024). "To rule out discrepancies between the in vitro and in vivo expression of GPNMB in the murine glioma cell lines used in this study, we additionally stained tumor brains from GL261 in vivo experiments." (PMID 38566120, 2024). "First, we quantified mRNA and protein levels of GPNMB in the RCAS-PDGFb and GL261 murine glioma models and compared the GPNMB levels to those of naïve, primarily cultured astrocytes and microglia of respective neonatal and adult mice as controls." (PMID 38566120, 2024). "Overexpression of GPNMB by retrovirus transfection in glioma cells is accompanied by MMP-3 and MMP-9 increase, both increasing metastasis and cancer invasion." (PMID 34054862, 2021). "GPNMBhigh macrophages can also secrete GPNMB to promote the PN-MES transition of glioma cells." (PMID 41174767, 2025). "Using published data bases of human glioma, the elevated levels in TAMs could be confirmed and the GPNMB expression correlated with a poorer survival." (PMID 38566120, 2024). "Within the glioma, we also found a population of GPNMB+/IBA1− cells." (PMID 38566120, 2024). "To determine whether GPNMB was upregulated in the murine TME, we used flow-cytometry to detect extracellular membrane-bound GPNMB of isolated cells from the tumor region of a separate WT mice cohort (n = 6) injected with unlabelled RCAS-PDGFb glioma cells." (PMID 38566120, 2024). "This activity of GPNMB could explain our in vivo observation, namely the reduced levels of Foxp3+ T regs and PD-1+ T cells in the glioma tissue combined with increased levels of cytotoxic cells, CD8+ cells and proliferating T cells." (PMID 38566120, 2024). "We therefore analyzed the role of GPNMB in host-derived glioma expansion." (PMID 38566120, 2024). "Using the PDGFb-driven replication-competent avian sarcoma-leukosis virus/ tumor virus A (RCAS/Tv-a) murine high-grade glioma model injected into GPNMB-KO and control mice, we demonstrate that host-derived GPNMB is of detrimental importance for glioma growth and immune cell composition." (PMID 38566120, 2024).
glioma (continued). "Studies have demonstrated that GPNMB was capable of blocking T cell stimulation via direct cell-cell intercommunication of antigen-presenting cells (APCs) and T cells resulting in immunosuppressive milieu in gliomas." (PMID 35419058, 2022). "Recent evidence has suggested that GPNMB‐si is an influential factor that could inhibit the progression of glioma." (PMID 37786733, 2022). "In addition, CCL5 and GPNMB have both been reported to play a role in glioma invasion, migration, and recurrence." (PMID 30151353, 2018). "The expression of GPNMB has been reported in tumor cells for different cancers, including glioma." (PMID 25658639, 2015). "The data from our GL261 glioma model suggests that GL261 cells express GPNMB at a very high level." (PMID 25658639, 2015). "GPNMB showed more than a 10-fold increase in the induction of protein expression compared to normal brain samples in cases of glioblastoma multiforme, the highest-grade glioma." (PMID 28347118, 2015). "Glioma-associated antigens targeted by immunotherapeutic approaches include cell adhesion molecules, matrix proteins, and growth factor receptors, such as tenascin, wild-type epidermal growth factor receptor, its glioma-associated variant, epidermal growth factor receptor variant III, and GPNMB." (PMID 20809959, 2010). "Thus, we could compare glioma cell lines with high and low levels of intrinsic GPNMB expression in our ex vivo models." (PMID 38566120, 2024). "Clinical Trials: Emerging therapeutic strategies targeting GPNMB, including CAR-T cell approaches for glioma and bispecific antibodies for NSCLC, hold potential to redefine cancer treatment paradigms." (PMID 41180454, 2025). "Here, we show that GPNMB is predominantly expressed by TAMs in human glioblastoma multiforme and the murine RCAS-PDGFb high grade glioma model." (PMID 38566120, 2024). "Nevertheless, in their RCAS-PDGFb glioma mouse model, as well as in human GBM samples, GAMs were the major source of GPNMB secretion in all paired experimental samples." (PMID 35419058, 2022). "Out of the 13 signature genes, ATP6V1E1, EIF3D, ERCC1, GPNMB, MTDH, PCNA and NEDD9 have been reported to play crucial roles in various pathways and mechanism of glioma." (PMID 31632497, 2019). "Furthermore, GPNMB has been shown to inhibit T cell activation via direct cell-cell interaction of antigen-presenting cells and T cells, and could thus contribute to the immunosuppressive milieu in gliomas." (PMID 25658639, 2015). "We used organotypic brain slices (OBS) inoculated with glioma cells to study the impact of GPNMB in microglia without the contribution of infiltrating peripheral cells." (PMID 38566120, 2024). "To further analyze the expression of GPNMB in glioma tissue, we stained slices from GBM and trauma/non-tumor patients with antibodies against IBA1 and GPNMB." (PMID 38566120, 2024). "Glycoprotein Nonmetastatic Melanoma Protein B (GPNMB) was identified as a prominent factor upregulated in TAMs of mouse experimental glioma models and human glioma tissue." (PMID 38566120, 2024). "We compared GPNMB expression of TAMs with microglia from age-matched naïve animals and separated them from non-immune cells (CD45−CD11b−) which are either predominantly glioma cells in the tumor tissue or neurons and macroglia in the normal brain tissue." (PMID 38566120, 2024). "However, in the RCAS-PDGFb glioma mouse model, as well as in human GBM samples GAMs were the predominant source for GPNMB expression in all tested paired samples." (PMID 25658639, 2015). "We used a genetically engineered mouse model of adult PDGFb-driven gliomas based on RCAS/Tv-a to implant primary RFP-labeled glioma cells into KO (n = 8) and respective WT control mice (n = 7), to determine the impact of host-derived GPNMB for glioma formation and growth." (PMID 38566120, 2024).
glioma (continued). "Here we present GPNMB and SPP1 as possible new targets and could show that these genes are highly expressed in GAMs in different glioma mouse models, in human GBM, and that high expression of these genes is correlated with shorter glioma-patient survival." (PMID 25658639, 2015).